ENO3 (enolase 3)
Diseases named in the same sentence as ENO3 in open-access papers (continued):
Sharing a sentence is not in itself a finding about the gene and the disease.
cancer (13 papers, 2014 to 2025). A tumor composed of atypical neoplastic, often pleomorphic cells that invade other tissues. "Thus, down-regulation of ENO3 gene expression and subsequently the encoded protein may prevent the growth of cancer cells." (PMID 27635343, 2016). "Enolase (ENO3), a metalloenzyme essential for glycolysis, is abnormally expressed in various cancers, and its overexpression has been shown to mitigate ferroptosis." (PMID 38612245, 2024). "The complex regulation among LINC00174, miR-2467-3p, and ENO3 can be critical for cancer cell survival and proliferation, and interfering with this regulatory network can be a promising approach to developing effective cancer therapies." (PMID 37448887, 2023). "The cancer-promoting mechanism of LINC00174 is related to targeting miR-2467-3p to promote ENO3 protein levels." (PMID 37448887, 2023). "β-enolase (ENO3) is a metalloenzyme that functions during glycolysis and has been revealed ectopic expression in different cancers." (PMID 35004693, 2021). "The results of RT-PCR indicated that GPC1, STC2, P4HA4, and ENO3 were upregulated in cancer cells while SPAG4 was downregulated in the five cancer cells." (PMID 33747908, 2021). "In contrast, ENO3, IDH2, IDH3G, and MDH2, genes that encode proteins that generally represses the proliferative, migratory, and invasive capacities of cancer cells, displayed the strongest positive correlations across nearly all cancers." (PMID 40806276, 2025). "ENO3, OSTC, and UROD serve as diagnostic or prognostic biomarkers in other cancers." (PMID 36826154, 2023). "Therefore, LINC00174 may play a critical role in regulating glucose metabolism and cancer cell proliferation by modulating miR-2467-3p expression and ENO3 protein levels." (PMID 37448887, 2023). "Of the 10 proteins, the preceding text showed that some studies identified RRM2, PLOD2, MKI67, MCM5, and CKD1 promoted cancer progression and FBP1, FBP2, ENO3, GPD1, and ASS1 inhibited cancer progression, which was consistent with our results." (PMID 33200655, 2020). "ENO3, as a member of the human enolase (ENO) family catalyzing the transformation of 2-phosphoglycerate to phosphoenolpyruvate during glycolysis, was reported to inhibit the growth of cancer cells." (PMID 35935823, 2022).
infection (2 papers, 2017 to 2020). The state of being infected such as from the introduction of a foreign agent such as serum, vaccine, antigenic substance or organism. "PGM2L1, ALDH8A1, and ALDHL18A1 on the other hand all displayed a delayed response and were only significantly upregulated by 16 h of infection, while ENO3 exhibited a downregulated response at 16 h." (PMID 28993767, 2017). "In particular, only a few glycolytic/glucanogenic genes exhibited an infection-induced change in expression (PGM2L1, LDHAL6B, ENO3, ALDH8A1, and ALDH18A1)." (PMID 28993767, 2017).
neurological disease (2 papers, 2016 to 2022). "Moreover, we identified 3 upregulated [ENO3, LPIN1 and SCN9A] and 3 downregulated [ATL3, CPT1C, and SGCB] RNAs whose genes have been implicated in neurological disorders." (PMID 34907471, 2022). "Interestingly, three hub genes (ENO3, ISOC1 and GNB3) in this cluster were enriched in the first annotation (hereditary disorder) and/or the second annotation (neurological disease) of diseases and functions." (PMID 27462267, 2016).
metabolic disease (1 paper, 2023). A congenital disorder (due to inherited enzyme abnormality) or acquired (due to failure of a metabolically important organ) disorder resulting from an abnormal metabolic process. "The miR-34a/ENO3 pathway may be a potential therapeutic target for hepatic IR and related metabolic diseases." (PMID 37960269, 2023). "Therefore, the regulation of miR-34a and its target gene ENO3 may be an effective approach to improve hepatic IR and prevent related metabolic diseases." (PMID 37960269, 2023).
ENO3 also shares sentences with these, for which no sentence is quoted: glycogen storage disease type 5 (2 papers); Insulin resistance (2); acinar cell carcinoma (1); breast carcinoma (1); cardiomyopathies (1); colorectal cancer (1); depression (1); geographic atrophy (1); glycogen storage disease type 13 (1); legionellosis (1); major depressive disorder (1); myopathy (1); skin melanoma (1); Tarui disease (1).